CXCR4 (C-X-C motif chemokine receptor 4)
Diseases named in the same sentence as CXCR4 in open-access papers (continued):
Sharing a sentence is not in itself a finding about the gene and the disease.
tumor (continued). "Thus, it is possible that CXCR4-expressing tumor cells could be prone to forming metastatic tumors in the liver and lungs." (PMID 38983932, 2024). "The MIF/CXCR4 axis could contribute to drug resistance in tumor invasion and metastasis." (PMID 39464891, 2024). "Notably, CD44 was highly expressed on the tumor-enriched stressed CD56bright state, alongside CXCR4 and CD74, possibly sensitizing this population to TME-mediated immunosuppression from CAFs, fibroblasts, endothelial and tumor cells, as noted by high scores for TGF-β signaling, hypoxia and ROS." (PMID 38956379, 2024). "Single-cell analysis and cell communication indicated that PPP1R16A is predominantly distributed in liver malignant parenchymal cells and may reshape the tumor microenvironment by enhancing macrophage migration inhibitory factor (MIF)/CD74 + CXCR4 signaling pathways." (PMID 39010084, 2024). "Moreover, we found that CXCR4 expression was positively correlated with tumor inflammation." (PMID 37626511, 2023). "Balixafortide is a potent, selective antagonist of CXCR4 with a high affinity for human CXCR4 receptor shown to be used to chemosensitize tumor cells to eribulin through the disruption of the SDF-1- mediated prosurvival signaling in the tumor microenvironment in preclinical studies." (PMID 36832085, 2023). "Therefore, CXCR4+ tumour cells tend to metastasize to organs that express CXCL12 via blood vessels." (PMID 37162544, 2023). "CXCR4 binds macrophage migration inhibitory factor (MIF), a factor implicated in the control of innate immunity, as well as CXCL12, a molecule well-known for its function in immunological surveillance, inflammatory response, tissue homeostasis, and tumor development and metastasis." (PMID 37190141, 2023). "Therefore, it is necessary to consider tumor staging as a potential confounding variable that could influence the interpretation of the impact of MRP2/CXCR4/PD-L1 co-expression on the overall patient cohort." (PMID 37444550, 2023). "The SDF1/CXCR4 axis, associated with cancer stem-like cells, is a target of cancer cells and can be overexpressed under pathological conditions; SDF1 is highly enriched in the bone marrow for CXCR4-positive hematopoietic stem cell (HSC) and also promotes tumor bone metastasis." (PMID 38004925, 2023). "Furthermore, the CXCR4/SDF1α axis promoted tumor lymph node metastasis." (PMID 37215990, 2023). "Although the mechanisms responsible for the nearly complete depletion of CAFs by OV-CXCR4-A are not fully understood, we hypothesize that they could be related to apoptosis of CXCR4-expressing CAFs after binding to the CXCR4 antagonist released from OV-CXCR4-A-infected tumor cells." (PMID 36875325, 2023). "Furthermore, ibrutinib could inhibit malignant B cells homing to spleens and lymph nodes through reducing homing chemokines CXCR4, which resulted tumor cells moving into the circulation and are killed by CAR T cells." (PMID 38143763, 2023). "Moreover, CXC ligand 12 (CXCL12, also called stromal cell-derived factor-1, SDF-1), which is produced by stromal cells and binds to C-X-C chemokine receptor type 4 (CXCR4) on the surface of tumor cells, has been reported to be essential for cancer pathogenesis." (PMID 37173977, 2023). "Focusing the study on the CXCR4 expression in the tumor stroma could generate more robust results." (PMID 37697316, 2023). "The inner PLGA nanosubmarines carried sorafenib via hydrophobic interaction, and the outer cationic lipid layer could adsorb AMD3100 (CXCR4 antagonist) by electrostatic interaction, which impart the tumor site-targeting properties to the material while blocking CXCR4 activity." (PMID 37452423, 2023). "Indeed, a prior study demonstrated the critical role of CXCR4 inhibition post-RT: A three-week course of AMD3100 treatment was more effective in inhibiting tumor growth when used after versus concurrently with a three-week regimen of fractionated RT with cisplatin." (PMID 36831366, 2023).
tumor (continued). "Finally, CXCR4 may prove to be a promising target for immunotherapy and cancer treatment since the delivery of siRNA to knock down this alpha chemokine receptor or CXCR4 antagonism has been shown to disrupt tumor–stromal interactions." (PMID 38004925, 2023). "Therefore, CXCR4 may promote tumor cell proliferation and metastasis when present in the cytoplasm or cell membrane." (PMID 37444550, 2023). "Interestingly, enhanced CXCL12-CXCR4 signaling in the BM was found to restrict MM cells from leaving the primary BM and re-entering the blood circulation, so increased CXCR4 expression in BM MM plasma cells led to reduced tumor dissemination and better prognosis 118-120." (PMID 37497001, 2023). "In addition, the CXCL12/CXCR4 axis may also promote cell proliferation, tumor growth, and angiogenesis." (PMID 37227446, 2023). "Finally, we validated the role of CXCR4 in positively correlating with tumor inflammation." (PMID 37626511, 2023). "This hypothesis is validated by other findings, implying that the HER2-mediated migratory potential of tumor cells could be repressed by anti-CXCR4 antibodies; on the other hand, HER2 suppresses ligand-mediated CXCR4 degradation and thereby potentiates the responding signaling." (PMID 35093187, 2022). "Therefore, the difference in the tumour environment of the lungs and brain may be the possible reason for the different expression level of CXCR4." (PMID 35045088, 2022). "In addition, repeated intravenous T22-DITOX-H6 administration in the CXCR4+ EC AN3CA orthotopic model induced a potent antimetastatic effect by displaying a reduction in primary tumor growth, and a blockage of metastasis development, again without systemic toxicity." (PMID 36612081, 2022). "Furthermore, CXCL12—a chemokine 12 able to bind to its cognate receptor CXCR4 determining the activation of several downstream signaling pathways which regulate tumor progression and metastasis—was found to be significantly downregulated in all the case series." (PMID 35203581, 2022). "It reported that the CXCR4+ neutrophils could promote tumour migration and support metastasis." (PMID 35184420, 2022). "Therefore, effective regulation of CXCR4 levels in tumor patients is important for stable disease." (PMID 35545781, 2022). "Finally, high CXCR4 tumor expression in recurrent HGSOC biopsies might be indicative for sensitivity to repeated chemotherapy." (PMID 35397601, 2022). "Inflammation may promote tumor development via the CXCR4 pathway." (PMID 35893797, 2022). "Additionally, the association between CXCR4 expression and advanced tumor staging was more apparent in Asian patients than in non-Asian patients." (PMID 35729596, 2022). "If such a tumor sink effect also occurs in patients injected with [68Ga]PentixaFor, this may have a relevant impact on “hot” and “cold” therapies targeting CXCR4, e.g., by safely increasing the amount of therapeutic activity but reducing side effects in organs with normal biodistribution." (PMID 35674738, 2022). "Antagonism of CXCR4 could potentially boost the chemosensitivity of tumor cells." (PMID 36164329, 2022). "In addition, CXCR4 inhibition could impact on the migration to BM of aged neutrophils, which have been reported to sustain angiogenesis, tumor progression, and metastasis." (PMID 35158948, 2022). "CXCR4 is considered a key factor in the malignant transformation of pancreatic intraepithelial neoplasia, and its expression level may be related to the grade of neoplasia." (PMID 36145541, 2022). "In addition, a 99mTc-labelled agent, [99mTc]TcAMD3465, has been explored for imaging CXCR4 expression in preclinical studies and has shown a significantly high tumour to background ratio; this will be useful in developing countries where PET imaging is not widely available." (PMID 36140541, 2022).
tumor (continued). "CXCL12 plays a key role in cancer progression by binding directly to CXCR4 expressed on cancer cells, promoting proliferation and invasiveness and indirectly by recruiting tumor immunosuppressive cells or by sequestering T cells in the tumor stroma as shown in several PDAC studies." (PMID 35954489, 2022). "Consequently, blocking the interaction of CXCL12/CXCR4 using neutralizing antibodies or targeting the expression of CXCR4 via RNAi/CXCR4 suppressed both regional and distant metastasis and prevented tumours growth in vivo." (PMID 36510219, 2022). "In addition, when pathological examination of the tissue after surgery indeed shows high expression of CXCR4, the residual (or possibly recurrent) tumor might be receptive to treatment with [177Lu]Lu-Pentixather." (PMID 33550492, 2022). "Therefore, interest might emerge in developing agonists of CXCR4 as anti-tumor drugs, especially if the effects specific for immune cells can be separated from general effects on angiogenesis and cell proliferation." (PMID 35565443, 2022). "Furthermore a high dichotomized distribution of CXCR4 positive tumor expression in recurrent cancer biopsies showed a significantly longer 6-month RFS rate (p = 0.018) in comparison to patients with low CXCR4 positive tumor expression." (PMID 35397601, 2022). "U87-stb-CXCR4/U87 (targeted-tumor/control tumor) ratios were higher for [111In]G5-X4 compared to [111In]G5-Ctrl in particular at 1 h 1.83 ± 0.13 vs. 1.25 ± 0.22 and 3 h 1.93 ± 0.02 vs. 1.35 ± 0.11, respectively, suggesting relatively faster uptake of [111In]G5-X4 in CXCR4-expressing tumors." (PMID 35336029, 2022). "[111In]G5-X4 showed higher accumulation in U87-stb-CXCR4 tumors compared to U87 tumors and [111In]G5-Ctrl at 48 and 120 h after injection, suggesting that interactions of targeted dendrimers with CXCR4 could prolong their tumor retention." (PMID 35336029, 2022). "For example, targeting CXCL12 with Pleraxifor, a C-X-C chemokine receptor type 4 (CXCR4) inhibitor, was shown to induce rapid T-cell accumulation among cancer cells and act synergistically with antibodies against Programmed death-ligand 1 (PD-L1), resulting in a strong reduction of tumor cells." (PMID 35892828, 2022). "Since SDF1 and apelin are downregulated only in muscles from cachectic and tumor-bearing mice, it would be interesting to learn whether and how these two pathways crosstalk in muscles, like occurs for their receptors CXCR4 and APJ during blood vessel maturation." (PMID 35406586, 2022). "Thus, activating caspase-3/GSDME-dependent pyroptosis specifically in CXCR4+ HNSCC tumor cells may represent a novel and enticing approach for the treatment of HNSCC patients." (PMID 35120582, 2022). "Importantly, the blocking of CXCL12/CXCR4 axis inhibits tumor growth and impairs metastasis." (PMID 35155581, 2022). "Moreover, neovascularization and tumor growth are reduced after CXCR4 neutralizing treatment." (PMID 35406582, 2022). "Furthermore, radiation selectively induced CXCL12, CXCR4 and FAPα expression in tumor tissues." (PMID 34976180, 2022). "In addition, pretreatment of AsPC-1 cells with BsNb PX4 or Nb CXCR4 resulted in a negative impact on cell proliferation, which indicated that the inhibitory effect of BsNb PX4 on tumour cells might involve blocking the CXCL12/CXCR4 signalling pathway." (PMID 36284271, 2022). "Thus, PI3K/Akt/mTOR pathway activation may be critically involved in CXCR4-mediated promotion of tumor aggressiveness in EOC." (PMID 35681259, 2022). "Moreover, the CXCR4/RhoA pathway is involved in tumor progression in digestive tract tumors." (PMID 35941537, 2022). "Previous studies have shown that CXCR4 promotes tumor cell proliferation and migration, mostly through its downstream ERK1/2 and AKT pathways, and therefore, we examined whether the dysregulation of KDM6B expression affects the ERK and AKT pathways in GC cells." (PMID 36564369, 2022).
tumor (continued). "Studies have demonstrated that the immune infiltration of B cells in the tumor microenvironment is associated with a survival advantage in patients with cervical, breast, and high-grade serous ovarian cancer; B cells are recruited through the binding of CXCL12 and CXCR4." (PMID 36188003, 2022). "Therefore, effective blocking of VEGR‐3 and CXCR‐4 may inhibit tumour cell metastasis by hampering intracellular proteins promoting adhesion." (PMID 36398426, 2022). "In line with tumor stroma interactions potentially playing a prognostic role, integrin pathway and chemokine signaling genes were found upregulated in stroma-rich poor-prognosis tumors, further supported by previous observation of CXCR4 and CXCR7 being upregulated in aggressive disease." (PMID 33919988, 2021). "Notably, we demonstrated a latent mechanism that exosomes could heighten the activation of the TLR2/NF-κB signalling pathway, resulting in the augment of CXCR4 expression and gathering of MDSCs into tumor microenvironment." (PMID 34659412, 2021). "Interestingly, only PXIV PCSCs expressed CXCR4, which, considering the tumor grading at the time of surgery, might indicate potential for a future metastatic progression." (PMID 34445612, 2021). "At the same time, a chronic hypoxia-induced increase in CXCR4 expression stimulates the proliferation of cancer cells and causes their migration and invasion, especially in combination with the chronic hypoxia-induced increase in CXCL12 expression in tumor cells." (PMID 33467722, 2021). "Furthermore, the SDF-1α/CXCR4 axis participates in tumour neoangiogenesis." (PMID 33919589, 2021). "Chemokines involved in the recruitment of multiple immune cell subsets (Cxcr4, Cxcl13, Ccl22) were upregulated in parallel with the co-stimulatory molecules Icos and the checkpoint receptor Ctla4, suggesting complex immunological changes in the tumor microenvironment (TME) in response to treatment." (PMID 34445452, 2021). "Therefore, we next tested whether human NANOG could regulate migration of tumor cells through CXCR4." (PMID 34638956, 2021). "Thus, CXCR4 overexpression promotes tumor growth of HCC by activating the c‐Met signaling pathway." (PMID 34555268, 2021). "A CAF-derived cytokine, CXCL12, interacts with CXCR4 (C-X-C-motif chemokine receptor 4), a protein overexpressed on the surface of cancer cells, whose interplay leads to the induction of the tumor angiogenesis through endothelial cell recruitment into the tumor niche." (PMID 33430277, 2021). "This could be explained by a proportion of transformed B cells depending fully on the MYC-oncogenic program and exponential tumor growth in Eμ-Myc animals, which could mask biologically relevant effects of additional CXCR4 hyperactivation as used in our experimental approach." (PMID 34363012, 2021). "However, limited studies were available to investigate the role of CXCR4 in tumor initiation." (PMID 34335790, 2021). "Therefore, targeting either molecule engaged in the control of CXCR4 expression on tumor cells or the downstream signaling could provide therapeutic options." (PMID 34943797, 2021). "Importantly, the scavenging function of ACKR3 has also been presented as a mechanism that is notably involved in the proper positioning of neurons in the developing mouse brain or in tumour metastasis via the egress of CXCR4-expressing cancer cells from the primary tumour site." (PMID 33466410, 2021). "Similarly, in glioblastoma and ovarian cancer, combination therapy of anti-CXCR4 and anti-PD-1 is also demonstrated to decrease populations of immunosuppressive tumor-infiltrating MDSCs, improve CD4+/CD8+ ratios, and confer a significant survival benefit compared to control and monotherapy arms." (PMID 35003065, 2021). "Therefore, the importance of CXCL12/CXCR4 signaling in HCC tumor cells can be foreseen." (PMID 34386499, 2021).
tumor (continued). "This suggests that Salmonella, which inhibits primarily AKT/mTOR signaling pathway, may represent promising a target agent preventing metastasis of many aggressive tumors that use CXCR4 for the guided migration of tumor cells from primary tumors to secondary colonization sites." (PMID 34220311, 2021). "Altogether, our in vivo studies in multiple xenograft settings suggest that CXCR4 total protein loss, regardless of its surface expression, result in compromised tumor growth, and chemotherapeutic drug paclitaxel can be even more effective to further sensitize these tumors under this condition." (PMID 33966046, 2021). "Furthermore, the fluorescence intensity of the Cy7@H-bMSCs group was significantly higher than that of the Cy7@bMSCs group, which suggests that the CXCR4/SDF-1α axis could improve migration of bMSCs to tumor tissues." (PMID 34069607, 2021). "Thus, considering CXCR4 and CXCR7 crosstalk in immune cells within the tumor microenvironment, some mechanisms underlying tumor resistance to immunotherapy may be impaired targeting the CXCR4/CXCR7–CXCL12 axis." (PMID 33937018, 2021). "While CXCR4 expression and its prognostic value has been far better characterized in the tumor interstitium than in its vasculature, it is possible that vascular CXCR4 may be a standalone biomarker of tumor development." (PMID 34793563, 2021). "Memory-like NK cells derived from both haplo-HSCT donors and cancer patients also display some adhesion/homing surface antigens such as CD38, CD18, CD49D, CD62L and CXCR4, which could favor their proliferative and migration capacity and have a role in mediating cytotoxicity against tumor cells." (PMID 33808051, 2021). "Several studies have also shown that high doses of anti-angiogenic agents could lead to hypoxia of the tumor microenvironment and upregulation of the CXCR4/CXCL12 axis and HIF-α levels due to excessive pruning of tumor vessels, which facilitates the recruitment of TAMs, MDSCs, and Tregs." (PMID 33746989, 2021). "However, multiple questions remain unsolved and thus, further exploration of the CXCL12/CXCR4/CXCR7 axes in tumor biology seems to be necessary for a comprehensive understanding of its impact on tumor progression, as well as on CSCs and the maintenance of their niche." (PMID 33530455, 2021). "Interestingly, FACS analysis of harvested tumor cells (CD326+ HCT116) did not display any induction of surface expression of CXCR4 in doxycycline group as compared to control again suggesting that the promotion of tumor growth was due to the overexpression of intracellular CXCR4 protein." (PMID 33966046, 2021). "Thus, spleen [68Ga]Pentixafor uptake could possibly be a marker for spleen CXCR4 expression and tumors with a higher inflammatory component and tumors that rely more heavily on a functional tumor microenvironment that recruits platelets and leukocytes." (PMID 34417915, 2021). "Therefore, the accumulation of CXCR4-expressing TAMs and MDSCs may be the reason why CXCR4 was mainly observed in tumor areas." (PMID 34676245, 2021). "Thus, our proposed mechanism for miR-139/CXCR4 conducted inhibition of tumor cell aggressiveness could be endorsed by repression CXCR4-mediated cancer cell stemness." (PMID 34070538, 2021). "Furthermore, whether Salmonella can reduce tumor cell metastasis by inhibiting the receptor of SDF-1 (CXCR4), the protein expression in Salmonella-treated tumor cells were measured." (PMID 34220311, 2021). "As a result, HIF stabilization in hypoxic tumor cells induces the expression of specific target genes encoding proteins that promote neo-angiogenesis (VEGF), metabolic changes (glycolytic enzymes and glucose transporters), stemness, EMT and metastasis (CXCR4, E-cadherin)." (PMID 33472628, 2021). "Finally, SDF-1 tumor expression moderately correlated with CXCR4 tumor expression." (PMID 33436863, 2021).